LINC00115 (long independently transcribed non-coding RNA 115)
Synonyms: FLJ22639; formerly NCRNA00115
Gene: Long non-coding RNA gene on chromosome 1 (586,945 to 827,989, reverse strand). Ensembl gene ENSG00000225880.
Diseases named in the same sentence as LINC00115 in open-access papers:
LINC00115 is named in the same sentence as 15 diseases in open-access papers, as found by Europe PMC text mining. Sharing a sentence is not in itself a finding about the gene and the disease. The quoted sentences say what the papers report.
breast carcinoma (7 papers, 2018 to 2024). "We further investigated the underlying mechanism by which LINC00115 promotes breast cancer cell metastasis." (PMID 32175684, 2020). "Next, we ought to explore the underlying mechanism by which LINC00115 promotes breast cancer metastasis." (PMID 32175684, 2020). "LINC00115 was identified as a novel regulator of chemotherapy-resistant breast cancer stem-like cells and high LINC00115 expression is linked to a poor prognosis in breast cancer patients post-chemotherapy." (PMID 39676873, 2024). "LINC00115 has been demonstrated to be highly expressed in breast cancer and other cancers and is a poor prognostic factor of cancers." (PMID 38520019, 2024). "Here, we reveal that LINC00115 is upregulated in chemoresistant BCSC and high LINC00115 expression relates to a poor prognosis for breast cancer patients after chemotherapy." (PMID 38520019, 2024). "All these findings indicate that an elevated expression of LINC00115 is linked to chemotherapy resistance caused by BCSC and facilitates breast cancer lung metastasis." (PMID 38520019, 2024). "LINC00115 is upregulated in various cancers, including lung adenocarcinoma, retinoblastoma, prostate cancer, ovarian cancer, breast cancer, and glioma." (PMID 38520019, 2024). "LINC00115 has been reported to be an oncogene in various human cancers, including colorectal, glioma, cervical cancer, and breast cancer." (PMID 35184643, 2022). "Our results were consistent with previous studies that knockdown of LINC00115 inhibits cancer cell (breast cancer, ovarian cancer and colorectal cancer) proliferation and invasion." (PMID 34697900, 2021). "Our findings indicate that LINC00115 directly inhibits the expression of miR‐7 in breast cancer cells, while this regulatory mechanism has been also suggested in lung cancer." (PMID 32175684, 2020). "Together, our findings suggest that LINC00115 promotes breast cancer metastasis through modulating the expression of miR‐7 and KLF4." (PMID 32175684, 2020). "LINC00115 expression is increased in breast cancer tissue and promotes tumor cell migration and invasion by inhibiting miR‐7 expression." (PMID 32175684, 2020). "Thus, inhibition of LINC00115 in combination with SETDB1 inhibitors significantly improved the efficiency of paclitaxel chemotherapy in an animal xenograft model of breast cancer metastasis." (PMID 39372872, 2024). "Furthermore, inhibiting LINC00115 in combination with SETDB1 inhibitor markedly improved the efficiency of paclitaxel chemotherapy in an animal xenograft model of breast cancer metastasis." (PMID 38520019, 2024). "LINC00115 forms an miR‐7/KLF4 pathway to promote breast cancer metastasis." (PMID 34697900, 2021). "We further confirmed that LINC00115 promotes breast cancer metastasis via inhibiting miR‐7." (PMID 32175684, 2020). "These suggest that LINC00115 promotes breast cancer through inhibiting miR‐7 expression." (PMID 32175684, 2020). "These suggest that LINC00115 promotes breast cancer cell metastasis through inhibiting miR‐7." (PMID 32175684, 2020). "Future studies should identify the exact distribution of LINC00115 in breast cancer cells." (PMID 32175684, 2020). "These suggest that LINC00115 acts as an oncogene in breast cancer and promotes cell metastasis." (PMID 32175684, 2020). "Collectively, our findings indicate that LINC00115 expression is increased in lymph node‐metastatic TNBC tissue compared with nonmetastatic TNBC tissue, as well as matched normal breast cancer tissue; LINC00115 promotes breast cancer cell metastasis by directly inhibiting miR‐7." (PMID 32175684, 2020). "Furthermore, we demonstrated that LINC00115 directly represses the expression of miR‐7, which has been confirmed to suppress breast cancer metastasis." (PMID 32175684, 2020). "Thus, targeting LINC00115 signaling factors may be a potential therapy strategy for patients with therapeutic-resistant breast cancer." (PMID 38520019, 2024).
breast carcinoma (continued). "Our findings uncover LINC00115 as a critical regulator of BCSC and highlight targeting LINC00115 and SETDB1 as a potential therapeutic strategy for chemotherapeutic resistant breast cancer." (PMID 38520019, 2024). "Because upregulation of LINC00115 assciates with TNBC metastasis in our findings, we directly detected its effect on breast cancer cell migration and invasion." (PMID 32175684, 2020). "In the present study, we found that LINC00115 expression is increased in TNBC tissue compared with matched normal tissue, and LINC00115 knockdown inhibits the migration and invasion of breast cancer cells." (PMID 32175684, 2020). "In a study for the treatment of paclitaxel-resistant breast cancer, it was observed that LINC00115 was strongly upregulated in paclitaxel-resistant BCSC, and that LINC00115 acted as an RNA linker recruiting the SETDB1/PLK3 complex to activate the HIF1α signaling pathway." (PMID 39372872, 2024). "Although we are not clear about the location of LINC00115 in breast cancer cells, the specific siRNAs can markedly inhibit the expression of LINC00115 and repress the migration and invasion of BT20 cells." (PMID 32175684, 2020). "Here, we report that LINC00115 expression is increased in triple‐negative breast cancer tissue compared with matched normal tissue, and LINC00115 knockdown suppresses breast cancer cell migration and invasion." (PMID 32175684, 2020). "LINC00115 promotes breast cancer metastasis by regulating the expression levels of miR-7 and KLF4; LINC00115 is significantly upregulated in HPV-negative cervical cancer cells and can promote the proliferation, migration, and migration of these cells; however, its role in RB remains unknown." (PMID 35184643, 2022).
lung carcinoma (4 papers, 2020 to 2025). "LINC00115 expression levels correlate with prognosis in human bladder and lung cancer patients." (PMID 35401659, 2022). "Otherwise, the previous study has also reported that LINC00115 may interact with miR‐7 to regulate lung cancer progression." (PMID 32175684, 2020). "LINC00115 was originally reported in lung cancer as a potential prognostic biomarker." (PMID 33193658, 2020).
glioma (3 papers, 2020 to 2022). A benign or malignant brain and spinal cord tumor that arises from glial cells (astrocytes, oligodendrocytes, ependymal cells). "In another study, LINC00115 was identified to be a critical regulator of glioma stem-like cell tumorigenicity." (PMID 33193658, 2020). "TGF-β induces the expression of several lncRNAs (LINC00645, LINC00115, UCA1, lnc-ATB) through the canonical or non-canonical signaling pathway to promote glioma progression." (PMID 35223453, 2021).
ovarian carcinoma (2 papers, 2021 to 2024). A malignant neoplasm originating from the surface ovarian epithelium. "Additionally, LINC00115 was shown to enhance stemness and suppress apoptosis in ovarian cancer stem-like cells through the upregulation of SOX9 and the inhibition of the Wnt/β-catenin pathway." (PMID 38520019, 2024). "For instance, LINC00115 can function as a ceRNA by acting as miR‐30a sponge to indirectly regulate SOX9 expression and promote stemness of ovarian cancer." (PMID 34697900, 2021).
bladder cancer (1 paper, 2021). "Jiang found that SNHG10, SNHG12, and LINC00115 were abnormally expressed in bladder cancer and that downregulation of SNHG12 expression was related to the inhibition of tumor proliferation." (PMID 34641864, 2021).
colorectal cancer (1 paper, 2021). A primary or metastatic malignant neoplasm that affects the colon or rectum. "For instance, LINC00115 serves as an oncogene and contributes to the progression of colorectal cancer by targeting miR‐489‐3p via the PI3K/AKT/mTOR pathway." (PMID 34697900, 2021).
lymph node metastasis (1 paper, 2020). "Considering that patients with LINC00115 dysregulation always presented with lymph node metastasis, we speculated that LINC00115 might play a pivotal role in CRC cell metastasis." (PMID 33193658, 2020).
prostate carcinoma (1 paper, 2021). A carcinoma that arises from epithelial cells of the prostate gland. "Our results showed that LINC00115 was significantly up‐regulated in prostate cancer tissues, which was significantly associated with a poor prognosis for prostate cancer patients." (PMID 34697900, 2021). "Rescue experiments further showed that LINC00115 inhibits prostate cancer cell proliferation and invasion via targeting miR‐212‐5p/ FZD5/ Wnt/β‐catenin axis." (PMID 34697900, 2021). "To explore the role of LINC00115 in prostate cancer, we firstly compared LINC00115 expression between normal tissues and PCa tissues by qRT‐PCR." (PMID 34697900, 2021). "Collectively, these data suggested that down‐regulated LINC00115 inhibits prostate cancer cell proliferation and invasion via targeting miR‐212‐5p/ FZD5/ Wnt/β‐catenin axis." (PMID 34697900, 2021). "In this study, the expression level of LINC00115 was measured in prostate cancer tissues and cells." (PMID 34697900, 2021). "Overall, LINC00115 was up‐regulated in prostate cancer tissues and cell lines." (PMID 34697900, 2021). "In addition, it was found that LINC00115 was significantly up‐regulated in prostate cancer cell lines, LNCaP, PC‐3, DU145 and 22RV2." (PMID 34697900, 2021). "Collectively, these data indicated that miR‐212‐5p might be a direct target of LINC00115 in prostate cancer." (PMID 34697900, 2021). "The present study provided clues that LINC00115 may be a promising novel therapeutic target for prostate cancer patients." (PMID 34697900, 2021). "Although the long non‐coding RNA LINC00115 was identified as an oncogene in several cancers, the expression and function of LINC00115 in prostate cancer have not been explored." (PMID 34697900, 2021). "We also innovatively uncovered that LINC00115 endogenously sponged miR‐212‐5p to elevate FZD5 expression, thus facilitating the malignant phenotype of prostate cancer, which might provide new insight into identifying the biomarkers for prostate cancer." (PMID 34697900, 2021).
triple-negative breast carcinoma (1 paper, 2024). An invasive breast carcinoma which is negative for expression of estrogen receptor (ER), progesterone receptor (PR), and human epidermal growth factor receptor 2 (HER2). "Correlative expression of LINC00115, methylation PLK3, SETDB1, and HIF1α are prognostic for clinical triple-negative breast cancers." (PMID 38520019, 2024).
tumor (9 papers, 2020 to 2025). "Further statistical analysis revealed that expression of LINC00115 was highly associated with T stage (p = 0.000), N stage (p = 0.000), and tumor–node–metastasis (TNM) stage (p = 0.000)." (PMID 33193658, 2020). "Since the differential expression of LINC00115 has been reported in different cancers, we also tested the expression of LINC00115 in RB cell lines and tumor tissues." (PMID 35184643, 2022). "Here, we found abnormal overexpression of LINC00115 in RB tissues and cell lines, and determined that LINC00115 silencing suppressed RB cell proliferation and migration in vitro and inhibited tumor growth in vitro." (PMID 35184643, 2022). "Herein, we found increased expression levels of LINC00115 in RB tissues and cells, and interference with LINC00115 expression inhibited the cell viability, migration ability, and tumor size in RB." (PMID 35184643, 2022). "Moreover, LINC00115 expression is higher in GBM tumour samples than in normal tissues and correlates with poor patient prognosis." (PMID 37891744, 2023). "We hypothesized that LINC00115 promotes RB cell proliferation, migration, and tumor growth by targeting the miR-489-3p/PFKFB2 axis." (PMID 35184643, 2022). "We hypothesized that LINC00115 promoted the RB cell proliferation, migration, and tumor growth by targeting the miR-489-3p/PFKFB2 axis." (PMID 35184643, 2022). "Furthermore, LINC00115 may also promote the malignant properties of tumor cells by sponging miR-607, which affects the expression of integrin subunit beta 1 (ITGB1), a molecule critical in tumor growth and metastasis." (PMID 40056285, 2025). "LINC00115 knockdown inhibits GSC proliferation and neurosphere formation in vitro and also inhibits tumour formation in the xenograft model." (PMID 37891744, 2023). "We confirmed that LINC00115 is upregulated in CRC and functions as an independent predictor of progression-free survival, leading to tumor progression and aggressiveness." (PMID 33193658, 2020). "To determine the expression of LINC00115 in TNBC tissues, we collected 48 pairs of tumor tissues and matched normal tissues from 48 patients with TNBC, 25 among whom presented with lymph node metastasis." (PMID 32175684, 2020). "Remarkably, LINC00115 KD significantly decreased MDA-MB-231 BCSC xenograft tumor growth and the formation of metastatic lung nodules and prolonged animal survival." (PMID 38520019, 2024). "The results showed that DLEU2 and LINC00115 were markedly overexpressed in ccRCC samples compared with normal tissues, whereas the expression levels of COL18A1-AS1 and SNHG10 were remarkably lower in tumor tissues than those in the adjacent non-tumor samples." (PMID 34721523, 2021). "We also observed that upregulation of LINC00115 was strongly related to the advanced TNM stage, larger tumor size, and lymphatic metastasis of CRC patients, thus suggesting that LINC00115 could be a prognostic factor for CRC." (PMID 33193658, 2020).
cancer (5 papers, 2020 to 2024). A tumor composed of atypical neoplastic, often pleomorphic cells that invade other tissues. "Accumulated evidence also demonstrated that LINC00115 functions as a miRNA sponge to regulate cancer stem-like cell stemness and progression." (PMID 38520019, 2024). "LINC00115 has been identified as a functional miRNA sponge to regulate miR-200s, miR-7, and miR-489-3 in cancer progression." (PMID 38520019, 2024). "More importantly, LINC00115 is a prognostic factor for these cancers." (PMID 38520019, 2024). "This new finding is consistent with the role of LINC00115 in other cancers." (PMID 35184643, 2022). "Previous studies have correlated cancer-related functions with AL360004.1, LINC00173, LINC01089 and LINC00115; however, none of them have been linked to the pathogenesis of AIS." (PMID 35401659, 2022). "The intersection set of the two gene lists includes 5 lncRNAs (EIF1AX-AS1, LINC00115, LINC01237, MALAT1 and LINC00528), among which only LINC00115 and MALAT1 have been experimentally validated to correlate with cancers according to the lncRNADisease2.0 database." (PMID 33318305, 2020).
LINC00115 also shares sentences with these, for which no sentence is quoted: cervical cancer (1 paper); colon cancer (1); esophageal squamous cell carcinoma (1); renal cell carcinoma (1).